IGF1 (insulin like growth factor 1)
Diseases named in the same sentence as IGF1 in open-access papers (continued):
Sharing a sentence is not in itself a finding about the gene and the disease.
cancer (continued). "Nutrition depletion reduced IGF-1 levels and risk of cancer, whereas infusion of IGF-1 abolished the protection against carcinogenesis provided by dietary restriction." (PMID 21729319, 2011). "The IGFs are potential regulators of carcinogenesis in several cancer types and IGF1 levels have been associated with cancer risk." (PMID 21437228, 2011). "On the contrary, reduced IGF-1 expression is linked to a reduction in cancer formation and metastasis." (PMID 23675206, 2010). "The first Network, which was built from 22 genes and received the highest IPA score, was centred on MAPK, RAS, AKT and IGF1 and associated with cancer, cell death and endocrine system disorders." (PMID 20525238, 2010). "A reduction in the amount of IGFBP3 available results in an increase in levels of free IGF-1, a factor associated with growth, proliferation, and an elevated risk of several cancers." (PMID 19603096, 2009). "IGF-1 signaling has been highly implicated in development of cancers, especially epithelial cell cancers (carcinomas)." (PMID 17953765, 2007). "Haplotype analysis of the IGF1 data showed only an association between one rare haplotype and cancer risk." (PMID 16404426, 2006). "It has, however, also been demonstrated that raised levels of insulin-like growth factor 1 are associated with increased risk of different cancers." (PMID 16175183, 2005). "The IGF-1Eb isoform has been proposed as a stress-responsive variant of IGF-1, yet its significance in cancer remains unclear." (PMID 42278323, 2026). "Furthermore, cancer-associated fibroblasts (CAFs) were identified as the major source of IGF1 in CCA microenvironment, essential for IGF1R-driven tumor progression." (PMID 41275311, 2025). "It was revealed that many miRNAs can be used as potential biomarkers, while others may contribute to metastasis regulation, targeting components of the IGF-1 bioregulation system and being implicated in cancer staging and/or progression." (PMID 41153350, 2025). "Aberrant IGF1 signaling has been implicated in the development and progression of various cancers." (PMID 41333209, 2025). "Taken together, these findings underscore IGF-1 as a metabolic onco-promoter and may serve as a potential biomarker for cancer risk assessment, screening, and prognosis." (PMID 41367907, 2025). "Nevertheless, additional research, especially targeted clinical trials, on the relationships between miRNA and IGF-1 may lead to improved diagnostic methods and new targeted therapies for a range of cancer types." (PMID 41153350, 2025). "Several studies have indicated that elevated IGF-1 levels may be linked to a higher risk of cancer and cancer mortality." (PMID 41374092, 2025). "Downregulation of the GH/IGF-1 signaling pathway in genetically modified knockdown and knockout models is generally associated with improved health in mice and reduced age-related pathologies like immunosensitivity and cancer." (PMID 39942843, 2025). "The diverse expression patterns of IGF1 isoforms in different types of cancer are significant, as IGF1 is moderately linked with an increased risk of total cancer in both men and women, with divergent associations observed for specific cancer types, as highlighted by Qian and Huo (2020)." (PMID 39796756, 2025). "Notably, elevated IGF‐1 levels in adipose tissue have been linked to metabolic disorders and an increased risk of cancer." (PMID 40159808, 2025). "Therefore, elevated serum IGF-1 levels have been linked to an increased cancer risk and have been proposed as complementary biomarkers for cancer susceptibility." (PMID 40566597, 2025). "Metformin lowers insulin levels and IGF-1 signaling, which can reduce the risk of cancer." (PMID 39940361, 2025). "Studies have shown that interactions between tumor-associated macrophages and cancer-associated fibroblasts (CAFs) can enable cancer cells to develop resistance to gemcitabine and paclitaxel in pancreatic and breast cancers, primarily through IGF-1/2 signaling pathways." (PMID 39861138, 2025).
cancer (continued). "Additionally, GH and IGF-1 promote cellular proliferation, increasing cancer risk, particularly colonic neoplasia, necessitating regular screening." (PMID 40842744, 2025). "Also consistent with a pro-tumoral role of the immune-suppressive state, the cells upregulate Igf1 (p < 10−6Table S3), which is associated with tumor progression in a diversity of cancer types." (PMID 41280683, 2025). "However, the direct link between circulating IGF-1 levels and cancer risk is a subject of ongoing scientific debate." (PMID 41002547, 2025). "Insulin-like growth factor-1 (IGF-1) is a biomarker linked to cancer risk and mortality." (PMID 40493660, 2025). "Alterations in IGF1 isoforms may persistently impact the cellular milieu, potentially leading to mutations in target genes that initiate cancer development." (PMID 39796756, 2025). "Moreover, insulin, which is structurally similar to IGF-1, is also related to cancer risk and outcomes, with hyperinsulinemia linked to a greater risk of cancer and cancer-related death." (PMID 38928185, 2024). "Several theories about the contributing factors to reduced longevity in larger dogs are consistent with increased risk of cancer in larger dogs including correlations between increased serum IGF-1 levels in larger dogs and downstream effects on growth, oxidative damage, and cancer risk." (PMID 38232117, 2024). "Additionally, IGF-1 signaling is implicated in the maintenance of cancer stem cells, which are often resistant to conventional therapies and contribute to tumor relapse." (PMID 39273251, 2024). "Insulin-like growth factor 1 (IGF-1) signalling is also implicated in cancer development." (PMID 38248845, 2024). "In addition to increasing cancer risk through IGF-1, insulin also influences carcinogenesis and progression by lowering sex hormone-binding globulin (SHBG) levels." (PMID 39290325, 2024). "Furthermore, individuals with elevated circulating levels of IGF-1 exhibit an increased risk for certain types of cancer." (PMID 39286267, 2024). "We acknowledge that through alterations in the IGF-1 system there is a plausible biological mechanism that may mediate positive associations between protein intake and cancer risk although the quantitative importance may be limited." (PMID 38643440, 2024). "Lower post-MBS insulin and IGF-1 levels likely reduce cancer risk." (PMID 39594685, 2024). "Targeting IGF1-associated lncRNAs has potential in cancer therapy." (PMID 39042294, 2024). "Cancer-associated fibroblasts (CAFs) also express Igf1 RNA in invasive lobular carcinoma models." (PMID 39273251, 2024). "The IGF-1 pathway has also been implicated in resistance to cancer therapies." (PMID 39273251, 2024). "The causal mechanism is unknown, but it is possible that insulin-like growth factor 1 (IGF-1) might be involved, as this has anabolic effects and has been associated with cancer risk in large-scale observational studies." (PMID 38538606, 2024). "Decreased levels of insulin and IGF-1 are associated with exercise and may contribute to the decreased risk of cancer with exercise." (PMID 38928185, 2024). "People with genetic mutations in the IGF-1 pathway, such as those with Laron syndrome, have a reduced cancer risk, better insulin sensitivity, and lower diabetes risk, but may face increased stroke and cardiovascular disease risk." (PMID 39200386, 2024). "Evidence showed that animal protein may increase the concentrations of insulin-like growth factor-1, a peptide hormone associated with an increased risk of cancers, including BC." (PMID 39718625, 2024). "It has been suggested that high protein intake may be related to cancer risk through alterations in the IGF-1 axis." (PMID 38643440, 2024). "This suggests a possible mechanism for how these dietary factors may contribute to the development of certain diseases, as IGF-1 has been linked to an increased risk of cancer and other health issues." (PMID 38313941, 2024).
cancer (continued). "Epidemiological studies suggest a link between GH/IGF-1 status and cancer risk." (PMID 36675591, 2023). "Additionally, this meta-analysis evaluated the association of IGF1 rs35767C>T with several types of cancer in eight studies with 11,257 CRC patients and 16,213 healthy controls which only three of studies were about CRC." (PMID 37284192, 2023). "Hence RAGE is associated with cancer incidence and increased cancer mortality rate in obese and diabetic patients by influencing dysregulated IGF-1 signalling and sustained inflammation." (PMID 37970208, 2023). "Epidemiological findings have indicated that elevation of serum concentration of IGF1 is related to increased risk of CRC because it can considerably increase the growth of cancer cells, suggesting evidence of the role of the IGF pathway in the risk and progression of carcinogenesis." (PMID 37284192, 2023). "Exercise also affects the IGF-1 signaling pathway involved in cancer proliferation/survival, expecially in different epithelial tumors thus explaining, at least in part, the molecular mechanisms underlying cancer prevention." (PMID 39086668, 2023). "Moreover, stromal cells such as cancer-associated fibroblasts (CAFs) and tumor-associated macrophages are major sources of tumor-derived IGF-1 in PDAC." (PMID 37373743, 2023). "Potential aetiologic mechanisms linking taller height to an increased cancer risk include more stem cells with an increased number of mutations during cell division, and insulin-like growth factor 1, which is a major determinant of height and organ size and of cancer risk." (PMID 36460776, 2023). "An association between IGF-1 levels and cancer risk has been demonstrated." (PMID 37895144, 2023). "While increased IGF1 levels as well as constitutive activation of the IGF1R are important risk factors in cancer, reduced activities of the GHR, IGF1R, insulin receptor and downstream mediators (e.g., AKT, mTOR, FOXO) have been associated with a prolonged lifespan." (PMID 37941907, 2023). "It has been debated whether growth hormone replacement treatment, leading to increased levels of IGF-1, may contribute to the observed increased cancer risk in PWS." (PMID 37575996, 2023). "The effect of polymorphisms in the IGF1 gene on endocrine IGF1 levels and cancer risk is variable." (PMID 37834331, 2023). "We postulated that life-long deficiency of IGF1 in LS might activate cancer-protecting pathways at the organismal level, including apoptotic and autophagic mechanisms." (PMID 37941907, 2023). "Increased IGF-1 levels could induce mutations in various cell lines, including thyroid cells, and contribute to the increment of cancer cases by stimulating cell proliferation, adhesion, and migration, and by inhibiting apoptosis." (PMID 37772697, 2023). "Our comprehensive analyses have identified a number of new targets for IGF1 action whose over- or under-representation in LS might be linked to cancer evasion and, possibly, extended lifespan." (PMID 37941907, 2023). "Circulating total IGF-1, a major determinant of free IGF-1 concentrations, is associated with increased risk of colorectal advanced adenomas and cancer, since increased free IGF-I alters mitogenesis and anti-apoptosis pathways in cells, thus favouring tumour formation." (PMID 37370812, 2023). "gp96 overexpression is reportedly linked to increased malignancy in a variety of cancers, since it chaperones key molecules that engage in tumor cell proliferation and invasion, such as insulin-growth factor 1 (IGF1), low-density lipoprotein receptor-related protein 6 (LPR6), and integrins." (PMID 35794988, 2022). "The IGF-1 axis has been linked to the development of several cancer types." (PMID 35715516, 2022). "This discrepancy suggests that prostate epithelial cells may be at an increased risk of cancer development or progression only after prolonged exposure to high concentrations of IGF-1." (PMID 35370981, 2022).
cancer (continued). "Diabetes, obesity, and cancer frequently coexist in part due to insulin resistance where excessive stimulation of the insulin/insulin-like growth factor (IGF-1) pathway might cause abnormal cell signaling and cancer growth." (PMID 35455439, 2022). "It is demonstrated that the interaction between tumor-associated macrophages and CAFs could facilitate cancer cells to gain gemcitabine and paclitaxel resistance in pancreatic and breast cancer in an IGF-1/2-dependent manner." (PMID 35488263, 2022). "In these cancer types, basic studies have also shown an association with IGF-1 signaling." (PMID 35370981, 2022). "Elevated IGF-1 levels have been associated with the development of cancer." (PMID 35573994, 2022). "In addition, IGF1/IGF1-R was found to a target associated with the PI3K/AKT pathway in the depression of cancer proliferation, subcellular distribution, invasion, and chemoresistance." (PMID 35280511, 2022). "In fact, calcium and IGF-1 in dairy products play critical roles in development and growth during childhood and adolescence, and several studies have investigated how dairy intake in early life relates to cancer risk." (PMID 35334890, 2022). "Evidence shows that some energy homeostasis genes may also regulate signaling pathways involved in cancer development, supporting their potential to modify the association between IGF-1 and IGFBP-3 and the risk of BC." (PMID 35115550, 2022). "Low protein intake had been shown to be more effective in lowering the IGF-1/mTOR nutrient-sensing pathway and is also associated with a reduction in cancer and mortality in the 65 and younger population and protein intake is a key determinant of circulating IGF-1 levels in humans." (PMID 33946428, 2021). "In a word, GH and IGF1 levels are associated with cancer risk." (PMID 34178997, 2021). "High IGF-1 has been associated with elevated incidence of a number of cancers." (PMID 34572814, 2021). "In radiotherapy for cancer, radiation resistance induced by GH and IGF1 signaling reduces the effectiveness of radiotherapy in many patients and may cause metastasis and cancer recurrence frequently." (PMID 34178997, 2021). "In addition, a diet with calorie restriction, leading to a decrease in endogenous insulin and IGF-1 levels, reduces the stimulation of mitogenic pathways, reducing the risk of cancer." (PMID 33562380, 2021). "The pivotal role that IGF-1 plays in cell growth and proliferation, combined with the apparent protection against post-natal development of malignancies conferred by congenital IGF-1 deficiency, suggests a possible involvement of IGF-1 in the development of cancer." (PMID 33557137, 2021). "Reduced activation of insulin and IGF-1-pathways has been linked to longevity and a reduction of cancer, but it remains unclear whether this is linked to reduced IGF-1 pathway activity or to improved insulin sensitivity." (PMID 33686453, 2021). "A plausible mechanism that could underlie the association between breast size and cancer prognosis may be an increase in IGF-1 levels." (PMID 33479372, 2021). "These interventions were selected based on hypotheses that weight loss and metformin might reduce cancer risk via IGF-1, a biomarker associated with cancer development." (PMID 34444833, 2021). "Further genetic epidemiology including fine mapping may help elucidate exactly by which mechanism variation at the IGF1 locus associates with risk of prostate and some other cancers." (PMID 33252839, 2021). "In addition, many studies have confirmed that genetic mutations in the IGF1 gene are associated with the occurrence and development of cancer." (PMID 34178997, 2021). "Some studies have indicated a clear association between cancer and the insulin/IGF-1 axis." (PMID 33479372, 2021).
cancer (continued). "The down-regulation of the GH/IGF-1/insulin system decreases cancer risk and increases longevity in animal models; however, in humans the results are somewhat contradictory, although genetic studies of the GH/IGF-1/insulin system support their involvement in human longevity." (PMID 34695806, 2021). "Studies also found that the presence of congenital IGF-1 deficiency, equivalent to reducing IGF-1 through fasting (see Nutrient Levels Influence Mechanisms that Promote Cancer Development), could confer protection against tumor progression." (PMID 32370764, 2020). "However, recent studies provide evidence that stromal cells such as cancer-associated fibroblasts (CAFs) and tumor-associated M2 macrophages are the major sources of tumor-derived IGF-1 in PDAC." (PMID 32414222, 2020). "Next, we performed sex-stratified analyses of the association of log2-transformed plasma IGF1 levels with mortality from specific causes of death, namely death from infectious diseases, cardiovascular mortality, death from malignancies, and other, miscellaneous causes of death." (PMID 31973007, 2020). "In addition, several epidemiological studies have shown that higher levels of IGF-1 are associated with an increased risk of different types of cancer." (PMID 32824177, 2020). "In tumoral stroma, IGF-1 is mainly secreted by cancer-associated fibroblasts (CAFs)." (PMID 32899449, 2020). "In adults high levels of IGF-1 are associated with increased cancer risk and CV diseases." (PMID 31417661, 2019). "However, previous studies revealed that the effects of IGF-1 variants on the risk of some cancers were modified by sex or menopausal status." (PMID 31787098, 2019). "IGF-1 plays a role in carcinogenesis and leads to an increased risk of cancer." (PMID 31231120, 2019). "Fasting, which is defined as a short-term transient total absence of food, has shown evidence of being more efficient in reducing levels of IGF-1 and glucose than any prolonged caloric restriction and, furthermore, favors chronic weight loss that is highly deleterious to most cancer patients." (PMID 31284426, 2019). "Tumor progression relies on close interaction and communication between cancer cells and cancer-associated fibroblasts (CAFs) through several mechanisms, including paracrine signals (transforming growth factor-β, IGF-1, exosomes), cell-to-cell contact and ECM remodeling." (PMID 31109009, 2019). "Moreover, high IGF1 concentrations have been implicated in cancer, whereas IGFBP3 has a protective effect." (PMID 30759961, 2019). "The IGF1 SNPs affect cancer susceptibility mainly by influencing the serum levels of IGF1." (PMID 30654740, 2019). "IGF1 rs2195239 and rs2162679 were associated with overall cancer risk based on present studies." (PMID 30654740, 2019). "Pristimerin (PRI) has been demonstrated to inhibit the growth of several cancer cells, but its role and underlying mechanisms in the IGF‐1‐induced UM cell proliferation are largely unknown." (PMID 31508890, 2019). "In addition to its role as a mediator in metabolism, IGF-1 is also implicated in developmental disorders, a variety of diseases other than metabolic disorders, or cancers." (PMID 30018981, 2018). "Also, in patients undergoing liver resection for HCC, preoperative low and delayed recovery of IGF1 levels at 30 days after surgery were independent risk factors for early recurrence of this cancer." (PMID 29702590, 2018). "The molecular mechanism via which the rs1520220 C allele increases plasma IGF1 levels and thus cancer risk remains unclear." (PMID 30111277, 2018). "Therefore, in the canine species, a single application of PRGF is safe for parental use with respect to local and systemic IGF-1 levels and cancer risk." (PMID 30208586, 2018). "Indeed, in different cancers, such as breast, colon, or prostate cancer, hyperinsulinemia and obesity induced by insulin and IGF1/2 are associated with poor prognosis." (PMID 30186236, 2018).